RFX1 (regulatory factor X1)
Diseases named in the same sentence as RFX1 in open-access papers (continued):
Sharing a sentence is not in itself a finding about the gene and the disease.
infection (11 papers, 2013 to 2025). The state of being infected such as from the introduction of a foreign agent such as serum, vaccine, antigenic substance or organism. "The RFX1 protein regulates the immune response in mammals and is response to infection by human hepatitis B virus, as well as cell-differentiation events in fission yeast." (PMID 30337955, 2018). "Moreover, RFX1 (a miR-346 predicted target gene) was found to be significantly downregulated (p < 0.05) after 48h infection, and miR-346 was found to have a role in this downregulation." (PMID 29867904, 2018). "Therefore, IL18 and RFX1 were more likely to be regulated by the poorly represented miR-346 in our infection model." (PMID 29867904, 2018). "Furthermore, we overexpressed Rfx1 in PMAs by lentivirus vector pLV-Rfx1 infection." (PMID 37733446, 2023). "GM-2 and GM-3 were predominantly associated with columnar epithelial responses and included regulators such as ATF2, CDX2, FOXJ2, and AHR, with infection-induced up-regulation of TFs such as SPI1, ESRRA, RFX1, and RARA." (PMID 41042872, 2025). "On the other hand, after 48h infection, IL18 and RFX1 appeared significantly downregulated in THP-1-derived macrophages infected with both L. (L.) infantum MHOM/TN/80/IPT1 and L. (V.) sp." (PMID 29867904, 2018). "Only RFX1 and IL18 genes showed significant downregulation after 48 h infection." (PMID 29867904, 2018).
adenocarcinoma (2 papers, 2011 to 2021). A common cancer characterized by the presence of malignant glandular cells. "CDX2, a NOTCH-1regulated gene involved in Barret's adenocarcinoma progression, is negatively regulated by RFX1." (PMID 33964962, 2021). "We further investigated the status of Rfx1 in human esophageal epithelium and in different precursor lesions leading to adenocarcinoma." (PMID 21935353, 2011). "The percentage of Rfx1 positive nuclei in adenocarcinoma also decreased relative to normal esophageal tissue, with virtually no staining of the epithelial cells in 18 of 20 samples (p≤0.0001) and sporadic staining of the stroma." (PMID 21935353, 2011).
RFX1 also shares sentences with these, for which no sentence is quoted: Bardet-Biedl syndrome (3 papers); ciliopathies (3); coronary artery disease (2); HIV-1 infection (2); Anxiety (1); astrocytic tumor (1); Ataxia (1); Autoimmunity (1); bare lymphocyte syndrome (1); Barrett esophagus (1); cervical squamous cell carcinoma (1); COVID-19 (1); depression (1); endometrial cancer (1); ependymal tumor (1); gastric cancer (1); hearing loss (1); heart disease (1); heart failure (1); Hypertension (1); inflammatory bowel disease (1); lupus-like syndrome (1); malaise (1); melanoma (1); MERRF syndrome (1); myoclonus epilepsy (1); Obesity (1); obstructive hydrocephalus (1); pancreatic cancer (1); pheochromocytoma (1).
A further 6 diseases each share a sentence with RFX1 in 1 paper.